GJB2 (gap junction protein beta 2)
Diseases named in the same sentence as GJB2 in open-access papers (continued):
Sharing a sentence is not in itself a finding about the gene and the disease.
hearing loss (continued). "Mutations in GJB2 gene are usually associated with non-syndromic hearing loss (NSHL)." (PMID 35734583, 2022). "Pathogenic mutations in the Gjb2 and Gjb6 genes, encoding connexin 26 (Cx26) and connexin 30 (Cx30), respectively, have been linked to the most frequent monogenic hearing impairment, nonsyndromic hearing loss, and deafness DFNB1." (PMID 36016655, 2022). "However, few studies have examined the non-coding exon 1 of GJB2 in Chinese patients with hearing loss." (PMID 36568381, 2022). "GJB2-related hearing loss (n = 75 pairs), cystic fibrosis (n = 15 pairs), thyroid dyshormonogenesis (n = 12 pairs), and thalassemia (n = 16 pairs) were the most common conditions found in the ARCs, which correspond with the related gene carrier frequencies identified in individuals." (PMID 36072675, 2022). "However, to date, in Russia, there are relatively few studies that focus on applying MPS methods to elucidate the genetic factors underlying non-GJB2-related hearing loss." (PMID 36555390, 2022). "Thus, the molecular etiology presented with high heterogeneity with the leading causes to be SLC26A4 and GJB2 genes in the Chinese hearing loss population." (PMID 35982127, 2022). "GJB2 mutations cause about 50% of non-syndromic hearing loss." (PMID 36187349, 2022). "First, GJB2 is the most common gene causing congenital hearing loss." (PMID 33639928, 2021). "Variants in the GJB2 gene are responsible for up to 30% of non-syndromic hearing loss." (PMID 34440441, 2021). "Though relatively rare, the GJB2 c.35delG homozygous mutation, which is the most prevalent mutation in Caucasians, could also contribute to late postnatal onset hearing loss." (PMID 33718389, 2021). "Interestingly, previous results showed that individuals with a heterozygous pathogenic GJB2 variant are two times more prevalent among those with hearing loss compared to normal-hearing individuals." (PMID 34062854, 2021). "A hitherto undiscovered variant could, in part, explain the cause of hearing loss in patients and would mean reclassifying them as patients with GJB2 biallelic pathogenic variants." (PMID 34062854, 2021). "While the several progression type hearing loss caused by certain GJB2 genotypes might be treated by gene therapy effectively still in adults, the timing of gene delivery in utero or after birth is imperative in most patients." (PMID 34356098, 2021). "Mutations in the GJB2 gene are the most common cause of human autosomal hereditary hearing loss." (PMID 35345836, 2021). "Another family and many more sporadic cases with the GJB2 c.235delC homozygous mutation and late-onset milder hearing impairment may provide the possibility to decipher the molecular mechanism." (PMID 33718389, 2021). "The problems and limitations of diagnosing hereditary hearing loss have been known for some time due to the fact that there is a higher prevalence of individuals with a heterozygous pathogenic GJB2 variant among patients with hearing loss than there is among the normal-hearing population." (PMID 34062854, 2021). "However, a subset of GJB2 (Cx26) variants is not only associated with hearing loss but also with severe skin diseases; moreover, these GJB2 variants are inherited autosomal dominantly and classified as syndromic hearing loss." (PMID 34360596, 2021). "The identified GJB2 variant has been most commonly associated with sensorineural hearing loss." (PMID 35011571, 2021). "It is also estimated that up to 50% of hearing loss is due to GJB2 variants in prelingual deafness." (PMID 34695157, 2021). "The distribution of Connexin 26 (GJB2) mutations varies greatly within ethnic groups, GJB2 c.35delG variant being present in 60% of Caucasians, Northern Europeans, and Turkish people with hereditary hearing loss." (PMID 35126756, 2021).
hearing loss (continued). "Our previous study suggested that deletion of the Gjb2 gene in the early postnatal period causes microtubule abnormalities, which may be one of the mechanisms underlying the OC deformity of Gjb2-related hearing loss." (PMID 35345836, 2021). "In addition, a relationship between the expression level of GJB6 and the severity of hearing loss caused by GJB2 mutations has been suggested." (PMID 34356098, 2021). "The absence of the second pathogenic variant in the DFNB1 region and the diagnostic yield (22%) of the WES in the patients suggests that the cause of hearing loss may be found in genes other than those related to the GJB2 gene." (PMID 34062854, 2021). "Hearing loss in children caused by congenital cytomegalovirus infection, syndromic conditions including Pendred Syndrome, and non-syndromic genetic conditions such as hearing impairment associated with GJB2 mutations have shown to be successfully managed by CI." (PMID 32765579, 2020). "The homozygous p.V37I variant in GJB2 is prevalent in East and Southeast Asians and may lead to a broad spectrum of hearing phenotypes from mild-to-moderate hearing loss with reduced penetrance to profound hearing loss." (PMID 31541171, 2020). "The two most common variants known to cause hereditary hearing loss among Roma have been identified: the first is in the GJB2 gene, c.71G>A (p.W24*), which is also found in India, and the other is c.1331+2T>C in MARVELD2, described originally in Pakistani families." (PMID 32847582, 2020). "Interestingly, one additional homozygote for MANBA c.2158-2A>G was also detected in a group of 59 Roma patients with an already clarified cause of hearing loss, namely in a homozygote for GJB2 c.71G>A (p.W24*) variant." (PMID 32847582, 2020). "Recent study suggests that an enrichment of rare variants in hearing loss genes such as GJB2, SLC26A, or USH1G may contribute to explain these phenotypic heterogeneities." (PMID 32038468, 2019). "Another example of hearing loss where multiple cell types may be affected includes Connexin 26 and 30 encoded by Gjb2 and Gjb6, respectively, which appear to be expressed in intermediate and basal cells and, to a lesser extent, marginal cells." (PMID 31920542, 2019). "As the disease progression varies in time of onset and the severity of the hearing loss, we hypothesize that GJB2 mutations alter inner ear’s susceptibility to environmental stresses, the exposure to which accumulates over time." (PMID 31562289, 2019). "In other forms of Gjb2 mutations, EP changes were found to be associated with hearing losses." (PMID 31562289, 2019). "Abnormal opening of hemichannels caused by GJB2 mutations has serious consequences on the ability of cells to maintain homeostasis and are suspected to cause syndromic hearing loss that may lead to death in early childhood." (PMID 31827424, 2019). "To date, >100 GJB2 mutations have been linked to hearing impairment." (PMID 29361521, 2018). "Additionally, genetic variants with known associations with congenital hearing loss have been identified.Variations in GJB2, SLC26A4 and MT-RNR1 are the most common variants associated with NSHL in China." (PMID 29634755, 2018). "In fact, the only cases of UPD so far described as causative of hearing loss, affect GJB2 gene." (PMID 30622556, 2018). "Mutations of GJB2 and GJB6, encoding Cx26 and Cx30, respectively, are associated with hearing loss." (PMID 29534490, 2018). "Alternatively, mutations in other gap junction genes might modulate the pathogenicity of GJB2 mutations and contribute to hearing impairment via digenic or polygenic inheritance." (PMID 30576380, 2018). "In studies of GJB2-related hearing loss, the common pathologies are the failure of the tunnel of Corti (TC) to open and the disappearance of Nuel's space (NS), and these malformations of the organ of Corti (OC) have been observed both in humans and in transgenic mice." (PMID 29361521, 2018).
hearing loss (continued). "GJB2 mutations are the leading cause of non-syndromic inherited hearing loss." (PMID 30150563, 2018). "The GJB2 variant c.35delG, leading to premature protein chain termination, was unequivocally established by numerous studies as pathogenic and represents the most common cause of hearing loss worldwide." (PMID 29320412, 2018). "Next, target genomic capturing and next-generation sequencing for a panel of 127 genes related to hereditary hearing loss, which included the GJB2, GJB6, SLC26A, MTRNR1, and MTTS1 genes, were conducted to screen for the causative gene variant (s) of deafness in this family." (PMID 30068307, 2018). "We found a large number of patients with hearing loss that could be explained by GJB2 mutations in this population, due to the high degree of consanguinity." (PMID 30344259, 2018). "Interestingly, over 90 unique genes overall have been found to be associated with deafness, although mutations in GJB2, which encodes Cx26, are thought to account for almost 50% of all hearing loss cases, from severe to profound." (PMID 30622930, 2018). "In addition, approximately two-thirds of dominant GJB2 mutations cause syndromic hearing loss associated with diverse skin disorders, whereas only the remaining one-third of mutations cause ADNSHL4." (PMID 28102197, 2017). "K+-recycling defect is a long-standing hypothesis for deafness mechanism of Connexin26 (Cx26, GJB2) mutations, which cause the most common hereditary deafness and are responsible for >50% of nonsyndromic hearing loss." (PMID 28603488, 2017). "Whole-exome sequencing may effectively identify the causes of idiopathic hearing loss in patients bearing heterozygous GJB2 variations." (PMID 28821934, 2017). "Many reports claim that approximately 50% of autosomal recessive deafness is caused by either homozygous or compound heterozygous mutations in the DFNB1 locus (GJB2), which is often the only gene that is routinely screened in the clinical setting when there is a family history of hearing loss." (PMID 27838790, 2017). "Deafness-associated GJB2 mutations (coding Cx26) can be classified into two groups: those that produce non-syndromic deafness and mutations that produce hearing loss associated with other signs such as skin alterations, ocular, renal or thyroid disorders (syndromic deafness)." (PMID 27141831, 2016). "Due to the vital role of Cx26 in cochlear physiology, numerous studies have explored the correlation between the genetic basis of GJB2 mutations/polymorphisms and other types of hearing loss, such as noise-induced hearing loss (NIHL); however, the results have been contradictory." (PMID 26927086, 2016). "GJB2 is thought to be involved in noise-induced hearing loss (NIHL)." (PMID 26927086, 2016). "It has been proposed that GJB2 mutations causing autosomal recessive non-syndromic hearing loss seems to be ethnically specific, probably based on founder effects, contrary to GJB2 mutations related to syndromic hearing loss that seem not to be population specific." (PMID 27141831, 2016). "Although many genes have been associated with hearing loss, mutations in the DFNB1 locus are to be the most frequent cause of autosomal recessive hearing loss and routine sequencing of the GJB2 gene and testing of GJB6 gene deletions are recommended in EMQN best practice guidelines." (PMID 26896187, 2016). "Finally, 48.67% of the patients were identified with hereditary hearing loss caused by mutations in GJB2, SLC26A4, and mtDNA12SrRNA." (PMID 27247933, 2016). "However, in our study, 28.07% patients with the p.V37I -homozygous variation had severe-profound hearing impairment, and 40.81% with compound p.V37I plus other GJB2 pathogenic mutation had severe-profound hearing impairment." (PMID 26061099, 2015).
hearing loss (continued). "In the present study, we analyzed the spectrum and frequency of GJB2 variants in 1067 Chinese non-syndromic hearing loss subjects from Zhejiang Province in eastern China, and investigated the clinical and genetic characterization of patients with putative GJB2 mutations." (PMID 26043044, 2015). "However, with the increasing awareness of GJB2, reports have increasingly considered p.V37I to be pathogenic with a mild-to-moderate hearing impairment phenotype." (PMID 26061099, 2015). "Variants in the GJB2 gene among 1067 Han Chinese subjects with hearing loss." (PMID 26043044, 2015). "Importantly, the worldwide prevalence of biallelic GJB2 related hearing loss accounts for 17.3% of cases." (PMID 26439696, 2015). "In addition, it is anticipated that there are additional GJB2 mutation(s) associated with hearing loss among Chinese population." (PMID 26043044, 2015). "GJB2 alleles containing two cis mutations have been rarely found in non-syndromic hearing loss." (PMID 26088551, 2015). "In the present study, we carried out a systematic and extended mutational screening of GJB2 gene in 1067 Han Chinese subjects with non-syndromic hearing loss, and the resultant GJB2 variants were evaluated by phylogenetic, structural and bioinformatic analysis." (PMID 26043044, 2015). "In addition, a number of studies have addressed the progression of hearing loss associated with GJB2 mutations." (PMID 26061264, 2015). "This information may advance our understanding of the pathogenic mechanism of GJB2 mutations associated with hearing loss." (PMID 24337325, 2014). "Mutations in the GJB2 gene, encoding the gap-junction protein connexin 26 (Cx26), may lead to sensorineural hearing loss (HL) and hyperproliferative epidermal disorder." (PMID 24945352, 2014). "Dominant mutations in GJB2 may lead to various degrees of sensorineural hearing impairment and/or hyperproliferative epidermal disorders." (PMID 24945352, 2014). "The two GJB2 gene variants identified as causative for sensorineural hearing loss for the proband in Family 1 had been clinically confirmed prior to the contest, but were not disclosed to the participants, and therefore served as a validated disease-causing variant set." (PMID 24667040, 2014). "Detection of the p.V37I variant of GJB2 in 18.2% of Koreans with mild hearing loss strongly suggests its contribution to the pathogenesis of milder hearing loss, which might justify sequencing of GJB2 from these subjects in the Korean population." (PMID 23637863, 2013). "A total of 35.74% deaf patients showed evidence of genetic involvement, based on either genetic screening or family history, and 17.45%, 9.79%, and 8.51% of these patients were determined to have inherited hearing impairment caused by GJB2, SLC26A4, and mtDNA 1555A > G mutations." (PMID 24341454, 2013). "Our study strongly suggests that the p.V37I variant of GJB2 contributes to the pathogenesis of milder hearing loss and may justify sequencing of GJB2 from subjects with mild to moderate degree of hearing loss in the Korean population." (PMID 23637863, 2013). "Among the patients with homozygotic 35delG in GJB2 we found some rare mutations that may worsen their condition of hearing impairment." (PMID 23969527, 2013). "Although our work was based on small numbers of patients, the results may confirm the importance of GJB2 mutations in the etiology of hearing impairment in Belém - PA." (PMID 23503914, 2013). "GJB2 is the most prevalent causative gene, and the major (commonly found) gene mutations cause 30–40% of deafness while the remainder of hearing loss is the result of various rare genes/mutations that have been difficult to diagnose by the conventional one-by-one approach." (PMID 23967202, 2013).
hearing loss (continued). "In this study, a total of 35.74% deaf patients showed evidence of genetic involvement, based on either genetic screening or family history; 17.45%, 9.79%, and 8.51% of the patients were determined to have inherited hearing impairment caused by GJB2, SLC26A4, and mtDNA 1555A > G mutations." (PMID 24341454, 2013). "A total of 35.74% deaf patients showed evidence of genetic involvement based on either genetic screening or family history, and 17.45%, 9.79%, and 8.51% of the patients were determined to have inherited hearing impairment caused by GJB2, SLC26A4, and mtDNA 1555A > G mutations." (PMID 24341454, 2013). "Our results indicated that the p.V37I exclusive genotype of GJB2 may cause subclinical hearing impairment at birth and increases risk for postnatal PCHI." (PMID 22574200, 2012). "Genotypes of GJB2 gene in Tibetan patients with hearing loss and Tibetan controls." (PMID 22389666, 2012). "The most common hereditary cause of hearing loss is a mutation of GJB2." (PMID 22720014, 2012). "We investigated the effect ofmutations in GJB2 gene on theoutcome of cochlear implantation in a populationwith a high rate of consanguineous marriage andautosomal recessive nonsyndromic hearing loss.Two hundred and one children with profoundprelingual sensorineural hearing loss wereincluded." (PMID 22567367, 2011). "Moreover, among the recessive hereditary hearing loss genes, the high prevalence genes of GJB2 or SLC26A4 also can be found only one mutant allele in the congenital hearing loss or enlarged vestibular aqueduct syndrome patients." (PMID 20504331, 2010). "Two hundred and twelve patients, screened from 7133 cases of nonsyndromic hearing loss in China, with monoallelic mutation (mainly frameshift and nonsense mutation) in the coding region of GJB2 were examined for the GJB2 IVS1+1G>A mutation and mutations in the promoter region of this gene." (PMID 21122151, 2010). "Although these data fail to support a hypothesis that SLC26A5 acts as a modifier gene of GJB2-related hearing loss, the sample size is small and investigation of a larger population might be more informative." (PMID 19492055, 2009). "The novel DNA sequence variation g.56167A>G which is predicted to represent a synonymous p.S434S variation was found in this study in a patient with bilateral, progressive, mild to moderate sensorineural hearing loss who is also homozygous for the controversial p.V37I variation in GJB2." (PMID 19492055, 2009). "Moreover, upon audiometric testing, these nine patients presented non-progressive audiometric findings, similar to those of patients described in the literature, 43, 44 diagnosed with hearing impairment caused by mutation in the GJB2 gene." (PMID 18278224, 2007). "However, although the mutations in the GJB2 gene are responsible for up to 69% of autosomal recessive non-syndromic hearing impairment, a problem emerges when patients are identified with only one GJB2 mutant allele." (PMID 16336662, 2005). "They delineated the longitudinal auditory features of the highly prevalent GJB2 p.V37I mutation on a general population basis and confirmed the utility of newborn genetic screening in identifying infants with late-onset or progressive hearing impairment undetectable by newborn hearing screening." (PMID 40943139, 2025). "Overall, our data supports GS as a first-tier test for nonsyndromic hearing loss as it led to additional diagnoses missed by ES, including the identification of a 125 kb deletion upstream of GJB2, which further refines the region critical for GJB2 expression and function." (PMID 41367487, 2025). "Mutations in the GJB2 gene may cause skin abnormalities in addition to hearing loss." (PMID 38734626, 2024).